TLR9 (toll like receptor 9)
Diseases named in the same sentence as TLR9 in open-access papers (continued):
Sharing a sentence is not in itself a finding about the gene and the disease.
liver failure (3 papers, 2015 to 2025). A liver disease characterized by the liver losing or has lost all of its function. "Moreover, Dejager and Libert showed that TLR-9 signals caused hepatocyte exhaustion and hepatic failure by promoting TNF-α production." (PMID 25892855, 2015). "NLRP3 inflammasome-deficient mice, such as Caspase1−/−, Asc−/−, and Nlrp3−/− mice, showed comparably reduced induction of liver failure to Tlr9−/− mice." (PMID 26549942, 2015).
lung disease (3 papers, 2006 to 2022). "A complete absence of TLR9 non-synonymous polymorphism rs5743844 (Pro99Leu) in our study population corroborates with the report of Lee and group (2006) where neither controls nor lung disease patients carried the same polymorphism." (PMID 31365550, 2019). "In summary, DNA sensors, such as TLR9 and cGAS-STING, participate in the development of lifestyle-related diseases such as vascular, metabolic, kidney, and pulmonary diseases." (PMID 36176986, 2022).
lupus erythematosus (3 papers, 2022 to 2023). An autoimmune, connective tissue chronic inflammatory disorder affecting the skin, joints, kidneys, lungs, heart, and the peripheral blood cells. "Because anti-dsDNA autoantibodies are diagnostic of lupus erythematosus, it has long been hypothesized that DNA sensing in general, and TLR9 in particular, might play a role in disease." (PMID 37555846, 2023). "Interestingly, the TLR9 signaling limits the TLR7-mediated immune responses to ssRNA and CpG DNA self-antigens in B-cells in lupus erythematosus patients." (PMID 35955609, 2022).
mesothelioma (3 papers, 2022 to 2023). A usually malignant and aggressive neoplasm of the mesothelium which is often associated with exposure to asbestos. "The role of IL-12 and IFN-γ in this TLR9-induced protection against mesothelioma early growth was also analyzed with the same neutralizing antibodies." (PMID 36714124, 2022). "We observed that the treatment of M2 macrophages with the extracellular DNA of karonudib-exposed mesothelioma cells activated the macrophage NFkB pathway by inducing p-ikBa phosphorylation and subsequent p65 activation and this effect was TLR9-mediated." (PMID 37894329, 2023). "In contrast, IFN-γ neutralization did not modify TLR9-mediated prevention of mesothelioma growth (p = 0.93)." (PMID 36714124, 2022). "This is why, TLR-9 agonists might be reasonable candidates aimed at stimulating an antitumor response against the malignancy; as an example, CpG oligodeoxynucleotides injection showed strong activity on established AB1 mesothelioma model leading to long-term survival." (PMID 35785199, 2022).
metabolic syndrome (3 papers, 2018 to 2022). A cluster of metabolic risk factors for CARDIOVASCULAR DISEASES and TYPE 2 DIABETES MELLITUS. "Among them, TLR9 is specialized in the recognition of DNA, and its deficiency was recently reported to protect from the development of metabolic syndrome induced by HFD." (PMID 33574823, 2020). "Despite the risk of infection by the reduction of TLR9 cleavage, TLR9 or Unc93B1 has a potential to be a target of intervention/prevention against metabolic syndrome." (PMID 29997629, 2018).
metastatic colorectal cancer (3 papers, 2017 to 2023). "MGN1703 is a novel Toll-like receptor 9 (TLR9) agonist, belonging to the “immune surveillance reactivators” drugs, currently being tested in a phase 3 trial for metastatic colorectal cancer." (PMID 35011639, 2021).
metastatic melanoma (3 papers, 2019 to 2024). A melanoma that has spread from its primary site to another anatomic site. "The phase 1/2 ILLUMINATE-204 trial studied a combination of TLR-9 agonist tilsotolimod and ipilimumab in patients with metastatic melanoma refractory to anti-PD-1 therapy." (PMID 39602056, 2024). "The potential effectiveness of tilstolimod, a TLR9 agonist, was suggested in a phase I trial, which enrolled three patients with PD-1 refractory metastatic melanoma." (PMID 35742834, 2022). "A phase 1b trial investigated the combination therapy of TLR-9 agonist CMP-001 and pembrolizumab in patients with unresectable or metastatic melanoma with either stable disease after 12 weeks or progressive disease during or after anti-PD-1 therapy." (PMID 39602056, 2024).
necrotizing enterocolitis (3 papers, 2017 to 2022). Necrotizing enterocolitis (NEC) is a devastating disease that affects mostly the intestine of premature infants. "This pattern of expression for TLR4 and TLR9 is inversed in tissue from infants suffering from necrotizing enterocolitis (NEC) and might be of pathophysiological relevance." (PMID 34054875, 2021).
Nephropathy (3 papers, 2013 to 2022). A nonspecific term referring to disease or damage of the kidneys. "However, we hope that the presented data will help other scientists to conduct future analyzes to decipher the role of TLRs (including TLR9) in regulating inflammation and impaired immune responses leading to kidney damage." (PMID 36233099, 2022). "In a mouse model of doxorubicin-induced nephropathy, intravenous infusion of macrophages preactivated with a TLR-9 agonist could exaggerate renal injury." (PMID 33644078, 2021). "The infusion of toll-like receptor 9 (TLR9) agonist-activated macrophages exaggerated disease progression in doxorubicin-induced nephropathy in mice, whereas resting macrophages did not induce disease progression." (PMID 23390421, 2013).
non-alcoholic fatty liver disease (3 papers, 2022 to 2025). "Recent evidence has also demonstrated the contribution of TLR9 signaling to the pathogenesis of non-alcoholic fatty liver disease (NAFLD)." (PMID 36176986, 2022). "Further research indicates that LPS can activate toll-like receptors 4 and 9 (TLR4 and TLR9), subsequently triggering the NLR family pyrin domain-containing 3 (NLRP3) inflammasome, a process believed to be involved in the fibrotic progression of non-alcoholic fatty liver disease (NAFLD)." (PMID 38231771, 2023).
osteoporosis (3 papers, 2022 to 2024). A condition of reduced bone mass, with decreased cortical thickness and a decrease in the number and size of the trabeculae of cancellous bone (but normal chemical composition), resulting in increased fracture incidence. "Since CpG ODNs are often recognized by TLR9 and inhibit osteoclastogenesis, this study investigated the TLR9 dependence and anti-osteoclastogenic effect of iSN40 to validate its potential as an osteoporosis drug." (PMID 39768281, 2024). "Therefore, TLR9-independent osteogenetic activity of iSN40 is a favorable characteristic for osteoporosis therapy." (PMID 35630904, 2022).
pancreatic ductal adenocarcinoma (3 papers, 2018 to 2025). An infiltrating adenocarcinoma that arises from the epithelial cells of the pancreas. "Pancreatic ductal adenocarcinomas with high cytoplasmic TLR9 expression have a hazard ratio for cancer-specific death of 0.32 compared with TLR9-low cases (multivariate HR = 3.09 for low expression; p = 0.003)." (PMID 41465346, 2025). "Cox regression survival analysis of patients with pancreatic ductal adenocarcinoma related to clinicopathological characteristics and TLR1, TLR3, TLR5, TLR7, and TLR9 immunoexpression." (PMID 31314777, 2019).
pancreatitis (3 papers, 2017 to 2023). Inflammation of the pancreas. "Genetic deficiency of TLR9 alleviates pancreatic edema, inflammation, and pro-IL-1β expression in pancreatitis." (PMID 32076577, 2020). "The mean values among the patient groups were significantly higher (p < 0.001 for TLR9 and NF-κB), and the logistic regression revealed the diagnostic value for pancreatitis (p < 0.001)." (PMID 32076577, 2020). "While TLR9 increased 1.005 times, NF-κB increased 3.52 times the diagnosis of pancreatitis according the logistic regression analysis." (PMID 32076577, 2020). "Among TLRs, TLR4 and TLR9 play critical roles in pancreatitis through inflammasome activation." (PMID 28592850, 2017).
periodontal disease (3 papers, 2022 to 2024). "TLR9-mediated proinflammation is one of the novel proinflammatory pathways for DNA sensing in periodontal disease pathogenesis." (PMID 36207325, 2022).
pertussis (3 papers, 2013 to 2019). A contagious bacterial respiratory infection caused by Bordetella pertussis. "It has previously been shown that addition of the TLR9 agonist CpG to an alum-adjuvanted pertussis vaccine enhanced IgG1∶IgG2a antibodies, providing indirect evidence of enhanced Th1 responses." (PMID 23592988, 2013). "It shows that the presence and/or rapid recall of pertussis antibodies are crucial to protection and that TLR9 (better than TLR4 agonists) may improve current aP vaccines and thus possibly better protect adolescents and adults against pertussis." (PMID 31333656, 2019). "Addition of a TLR9 agonist to the acellular pertussis vaccine resulted in greater stimulation of B and T cells and a shift to Th1, as well as higher antibody titers, suggesting that an agonist of TLR9 is also a candidate to add to the current pertussis vaccines." (PMID 31921136, 2019).
plaque psoriasis (3 papers, 2019 to 2023). "IMO-8400 inhibits TLR7/TLR8/TLR9 under phase-II clinical trials in patients with moderate to severe plaque psoriasis." (PMID 31582899, 2019). "The oligonucleotide IMO-3100 antagonizes TLR7/TLR9, and IMO-3100 has completed trials in patients with moderate to severe plaque psoriasis (NCT01622348)." (PMID 31582899, 2019). "This future might not be so far away: monospecific TLR7 and TLR9 antagonists are currently under investigation for the treatment of dermatomyositis and plaque psoriasis." (PMID 33168071, 2020).
pneumococcal infection (3 papers, 2010 to 2022). Infections with bacteria of the species streptococcus pneumoniae. "The protective role of TLR2, TLR4, and TLR9 against pneumococcal infection is suggested by the results obtained from studies using either TLR2, TLR4, or TLR9 knockout or mutant mice." (PMID 35281442, 2022). "Wang and colleagues found that morphine treatment impairs TLR9-NF-κB signalling and diminishes bacterial clearance following Streptococcus pneumoniae infection in resident macrophages during the early stages of infection, leading to a compromised innate immune response." (PMID 20226064, 2010). "Thus, control of pneumococcal infection in the central nervous system apparently depends on the additive, cooperative activity of multiple cell surface (TLR2) and endosomal (TLR7, TLR9, and TLR13) receptors." (PMID 32209688, 2020). "To identify relevant TLRs, we tested mice lacking TLR3, TLR7, TLR9, or TLR13, as well as TLR7/9−/− double knockout (KO) mice, for their ability to control pneumococcal infection." (PMID 32209688, 2020).
polyp (3 papers, 2014 to 2015). A usually exophytic mass attached to the underlying tissue by a broad base or a thin stalk. "Initially, epithelial cells from the turbinate tissue from patients with CRSwNP showed a significantly lower percentage of cells expressing TLR9 compared to turbinate tissue from healthy controls and polyp tissue from patients with CRSwNP." (PMID 25133733, 2014). "Interestingly, epithelial expression of TLR9 was detected in turbinates from healthy controls and in polyp tissue, whereas TLR9 was absent in turbinates from CRSwNP patients." (PMID 25504259, 2015). "The lack of epithelial TLR9 activity at the site of polyp growth might therefore contribute to the virus induced polyp development seen among patients with CRSwNP." (PMID 25133733, 2014). "However, a similar TLR9 upregulation could not be induced in polyp derived epithelial cells." (PMID 25133733, 2014).
pregnancy disorder (3 papers, 2013 to 2026). A disorder that is related to pregnancy. "So far, previous research showed the participation of several single-nucleotide polymorphisms (SNPs) of TLR2, TLR4, and TLR9 in various diseases and pregnancy disorders." (PMID 23161283, 2013). "We found in our study that genetic changes, localized in SNPs from CSF2, FLT1, TFPI and TLR9 genes, were associated with PROM, when the results had been adjusted for APTT, PLT parameters or pregnancy disorders." (PMID 34828331, 2021). "One possible modification influencing gene function, which was also confirmed in case of TLR2, TLR4, and TLR9 genes in accordance to different diseases and pregnancy disorders, is the occurrence of SNPs within the genetic sequence." (PMID 23161283, 2013). "An additional comparison between the pPROM and tPROM cases showed that the C alleles for the CSF2, FLT1 and TFPI polymorphisms, and the T allele for the TLR9 SNP in different complex variants, were more common in the women with pPROM after adjusting for APTT, PLT parameters and pregnancy disorders." (PMID 34828331, 2021).
sarcoma (3 papers, 2023 to 2025). A usually aggressive malignant neoplasm of the soft tissue or bone. "Our work suggests that the combination of RT with a TLR9 agonist, such as CpG, warrants evaluation in a clinical trial of sarcomas and perhaps other cancers." (PMID 39133651, 2024).
sarcopenia (3 papers, 2022 to 2024). Progressive decline in muscle mass due to aging which results in decreased functional capacity of muscles. "The aim of this study was to evaluate the relationship between markers involved in different aspects of inflammation such as serum TLR4, TLR9 and Resolvin E1 levels and primary sarcopenia in geriatric patients and to compare the diagnostic accuracy of these biomarkers with the SARC-F score." (PMID 38910224, 2024). "Moreover, inhibition of SIRT1 is necessary for Toll-like receptor 9 (TLR9) dependent muscle fibrosis and sarcopenia in aged mice." (PMID 36818553, 2023). "Thus, targeting TLR9 could be a potential therapeutic approach for sarcopenia in aging." (PMID 38910224, 2024). "This is the first study to examine the relationship between primary sarcopenia and serum TLR4, TLR9 and Resolvin E1 levels and to compare the biomarkers with SARC-F." (PMID 38910224, 2024). "In patients undergoing maintenance hemodialysis (MHD), circulating mtDNA contents were significantly higher in sarcopenia patients, together with higher TLR9 and IL-6 expression, which demonstrated that mtDNA could be involved in the pathogenesis of MHD-related sarcopenia." (PMID 36499488, 2022).
Thrombocytopenia (3 papers, 2021 to 2023). A reduction in the number of circulating thrombocytes. "Comparison of Tlr9−/−Pld3−/−Pld4thss/thss mice to Tlr9+/–Pld3−/−Pld4thss/thss littermates and to Unc93b13d/3dPld3−/−Pld4−/− mice revealed that complete TLR9 deficiency significantly ameliorated some abnormalities caused by PLD3/4 deficiency, such as thrombocytopenia." (PMID 34620855, 2021).
uveitis (3 papers, 2018 to 2025). An inflammatory process affecting a part of or the entire uvea. "Empty AAV capsids over 2% trigger TLR9-mediated inflammation and gene therapy-associated uveitis, but this risk is mitigated by the AAVX platform with advanced purification and perioperative steroids validated in LUXTURNA trials." (PMID 41304743, 2025). "This was a case of grade 2 uveitis occurring 157 days after end of study treatment (TLR9 + tremelimumab), which was couched in a DLT table that caught our eye on manual reading of the report (case No. 16), and actually not within the searchable text." (PMID 31269983, 2019). "Surprisingly, even after stimulation, the expression of TLR9 was significantly lower in IOTB group as compared to non-uveitis controls (p = 0.01)." (PMID 30218032, 2018). "However, TLR2 and TLR9 stimulation showed lower proliferation of CD4+ Teff cells in non-uveitis TB patients, hinting towards the possible role of mycobacterial factors as immune modulators in patients with IOTB as well." (PMID 30218032, 2018). "However, in contrast to TLR2 and TLR9, the mRNA levels of TLR4 were significantly higher in IOTB (73.72 ± 53.33) as compared to non-uveitis subjects (2.44 ± 1.27) (p = 0.05)." (PMID 30218032, 2018). "Firstly, the cells in vitreous fluids showed lower expression of TLR2 and TLR9 in IOTB as compared to non-uveitis and non-TB uveitis groups." (PMID 30218032, 2018). "Interestingly, we observed a similar trend in expression of TLR9, with IOTB (1.55 ± 0.93) showing significantly lower mRNA levels of the receptor as compared to non-TB uveitis (268.5 ± 155.5) (p = 0.01) but not non-uveitis subjects (6.06 ± 3.4) (p = 0.2)." (PMID 30218032, 2018).
Venous thrombosis (3 papers, 2020 to 2023). Formation of a blood clot (thrombus) inside a vein, causing the obstruction of blood flow. "The TLR-9-inhibited and -deficient mice were less capable of resolving venous thrombosis after inferior vena cava ligation when compared with wild-type mice." (PMID 37508529, 2023). "TLR-9 deficient mice have been compared to wild-type mice with regard to their capability of resolving venous thrombosis." (PMID 37508529, 2023). "Application of TLR9 agonist was associated with smaller venous thrombosis in this model." (PMID 32264928, 2020). "When wild-type mice were subjected to a TLR-9 stimulant, early venous thrombosis resolution was accelerated." (PMID 37508529, 2023). "It has been found that mice with the deletion of TLR9 had significantly a larger venous thrombosis and increased leukocyte infiltration compared with wild-type mice." (PMID 32264928, 2020).
ZIKV infection (3 papers, 2017 to 2022). "In view of our results showing that other TLRs, such as TLR4, TLR8 and TLR9, are upregulated during ZIKV infection, in particular with the ZIKVAs strain, additional studies are needed to determine the precise involvement of TLR activation in ZIKV pathogenicity." (PMID 31282298, 2019).
acute coronary syndrome (2 papers, 2019 to 2021). Signs and symptoms related to acute ischemia of the myocardium secondary to coronary artery disease. "Interestingly, platelets from patients with acute coronary syndrome expressed higher levels of TLR9, which suggests a higher sensitivity of platelets from these patients to TLR9 agonists." (PMID 34360659, 2021).
acute leukemia (2 papers, 2021 to 2025). A clonal (malignant) hematopoietic disorder with an acute onset, affecting the bone marrow and the peripheral blood. "A phase I trial with the TLR9 agonist (GNKG168) supports the immunomodulatory capacity of a TLR9 agonists in vivo, showing that in children with acute leukemia and present minimal residual disease a unique immune activation pattern can be induced." (PMID 34149402, 2021).
acute liver failure (2 papers, 2017 to 2025). Rapid deterioration of liver function causing encephalopathy and coagulopathy. "Similarly, plasma from patients with acetaminophen-induced acute liver failure upregulated neutrophil TLR9 expression in vitro and this increase was abrogated by preincubation with DNase I40." (PMID 29234042, 2017).